MYC (MYC proto-oncogene, bHLH transcription factor)
Diseases named in the same sentence as MYC in open-access papers (continued):
Sharing a sentence is not in itself a finding about the gene and the disease.
cancer (continued). "The MYC gene is overexpressed in as many as 70% of human cancers, which makes MYC an attractive theoretical target for cancer treatment." (PMID 38424044, 2024). "Subsequent analysis revealed immune-suppressive pathways positively correlated with LM.SIG across pan-cancer datasets, including metabolism, DNA repair, and MYC signaling." (PMID 38664705, 2024). "There were two cancer-related pathways (pro-proliferative and anti-apoptotic) MYC Targets V1 and V2 that share most of their gene sets, which are perturbed at nominal concentrations between ca. 10–15 μM." (PMID 38577564, 2024). "We discovered that the 3′UTR of the c-MYC across many c-MYC-driven cancers is enriched with mRNA-stabilizing poly U sequences." (PMID 39123391, 2024). "We discovered that TAK-981 downregulated the expression of the currently undruggable MYC and effectively suppressed the growth of MYC-expressing KRAS-mutant cancers across different tissue types." (PMID 38992694, 2024). "BCL2A1 and c-MYC are both described to be relevant for cancer cell survival and additionally seem to correlate in a c-MYC overexpression context, indicating similar regulation of both genes and shared upstream signaling pathways." (PMID 39192247, 2024). "Here, the authors show that MYC amplification induces CDK4/6 inhibitors resistance through transcriptional regulation of KLHL42, leading to RB1 degradation and targeting MYC overcomes CDK4/6 resistance in preclinical cancer models." (PMID 38424044, 2024). "Our data support a potential for repurposing the anti-cancer, therapeutic JQ1 to inhibit MYC in a non-cancer setting." (PMID 38493137, 2024). "Amplification of MYC is present in 30–50% of high-grade BCs and is related to resistance in anti-cancer therapies; therefore, it is a useful predictive marker for drug and RFS (relapse-free survival (81." (PMID 38462658, 2024). "For instance, MYC downregulation has been previously reported as a survival strategy for cancer cells under conditions of limited energy resources." (PMID 38287309, 2024). "MYC protein levels decrease in cancer cells that are distant from blood vessels, and RNA interference-mediated MYC downregulation decreases necrotic cell death induced by oxygen and glucose deprivation." (PMID 38287309, 2024). "In fact, MYC expression is tightly regulated by MYB proteins, which highlights one important aspect of the manifold roles of MYB proteins in cancer-associated processes." (PMID 38835346, 2024). "Through the overexpression of SLC1A5, glutamine absorption is increased in K-Ras-driven cells, similar to the results observed in MYC-driven cancer cells." (PMID 39051546, 2024). "The most deregulated oncogene in human cancers is MYC but it has remained an elusive target in cancer biology for decades." (PMID 38321218, 2024). "Inactivation of NSD2 also engendered increased dependency on its paralog NSD1, which independently maintained AR and MYC hyper-transcriptional programs in cancer cells." (PMID 38464251, 2024). "Targeting the function of the MYC oncoprotein is expected to realize new and effective anticancer therapies that can be applied to a variety of cancers." (PMID 38240704, 2024). "Overall, our study elucidates the critical role of MED30 overexpression in orchestrating oncogenic transcriptional programs and highlights its potential as a therapeutic target for MYC-amplified cancer." (PMID 38766212, 2024). "For example, myelocytomatosis (MYC) is a notorious oncoprotein overexpressed in most of human cancers, and androgen receptor (AR) and forkhead box A1 (FOXA1) are pioneer factors in PRAD." (PMID 39436262, 2024). "Themolecules are based on connecting a known MYC binder to a VHL ligandor pomalidomide to induce MYC degradation in various cancer cellsknown to express MYC." (PMID 39698270, 2024).
cancer (continued). "Together with our recent study and here, the findings support that combination inhibition of SUMOylation and MEK comprehensively conquers MYC-expressing KRAS-mutant cancers by both immune-dependent and immune-independent antitumor responses." (PMID 39334463, 2024). "c‐MYC, a classical and well‐characterized proto‐oncogene, triggers metabolic reprogramming in cancer cells." (PMID 39534558, 2024). "With their far-reaching impact on every hallmark of cancer, RAS and MYC synergistically amplify the core mechanisms underlying tumorigenesis." (PMID 39164274, 2024). "Numerous studies have demonstrated the role of MYC as a crucial stress adaptation factor in KRAS-driven cancers." (PMID 39164274, 2024). "c-MYC is a well-known major driver of carcinogenesis and is one of the most commonly deregulated oncogenes identified in human cancers." (PMID 39031286, 2024). "MYC amplification or overexpression drives several pathways involved in cancer development and drug-resistance." (PMID 38200580, 2024). "Taken together, we concluded that CREPT and MYC are both highly expressed in different cancers, implying their possible interaction during tumorigenesis." (PMID 39615685, 2024). "Since MYC is hyper-activated in many cancers, this mechanism of oncogene-induced replication stress is likely to have an important role in cancer biology and potentially therapy." (PMID 38383676, 2024). "Together, these findings provide insights into structure-activity relationships of c-MYC, which open avenues towards the development of shape-shifting compounds to target c-MYC as well as other disordered transcription factors for cancer treatment." (PMID 38424045, 2024). "This review surmises that MYC inhibition would be beneficial in systemically combating metabolic reprogramming and immune evasion in various cancers." (PMID 38390324, 2024). "During this metabolic process, oncogenes such as YAP, KRAS, and c-MYC increase the expression of GLUT1 in cancer cells." (PMID 38841361, 2024). "Among the other members of its family, MYCN and MYCL, MYC is the most expressed and deregulated in cancers." (PMID 39482742, 2024). "Many of the cancer hallmarks are activated by MYC deregulation, including proliferation, genomic instability, cell survival, self-renewal, metabolism, invasiveness, immune evasion, and angiogenesis." (PMID 38674385, 2024). "Overall, these results demonstrated the anti-cancer potential of MP1 against MYC-amplified MB cells." (PMID 38200580, 2024). "In particular, cancer patients with high CSscores exhibited significantly higher enrichment scores of “DNA repair” (P < 0.001) and “MYC targets v1” (P < 0.001)." (PMID 39141443, 2024). "MYC-positive cancer can also be detected through real-time transferrin-based PET (Positron Emission Tomography) scans that utilize Gallium-68 Citrate." (PMID 38674385, 2024). "Prior findings of viral gene anticorrelation with MYC, STAT3, and BCL2A1 and lytic cell upregulation of cancer-associated stem-like pluripotency and host shutoff escapees were conserved in B958-ZHT." (PMID 38915538, 2024). "We turned our attention to the highly dynamic, cancer relevant and well-studied MYC locus, and its super enhancer." (PMID 38499482, 2024). "MYC is critical in controlling self-renewal, survival, and stem cell transformation in certain cancers." (PMID 38166947, 2024). "Current studies propose that MYC plays a crucial role in KRAS-driven cancers, although the connection between MYC and drug resistance in these types of cancers remains an unanswered question." (PMID 39457457, 2024). "Next, we examined the efficacy of combination treatment with trametinib and TAK-981 in MYC-expressing KRAS-mutant cancer cells." (PMID 38992694, 2024). "c-MYC, a transcription factor aberrantly expressed in over 70% of human cancers, was engineered into a doxycycline-inducible cassette in these cells, leading to increased c-MYC expression upon doxycycline treatment." (PMID 39729513, 2024).
cancer (continued). "By inducing the proteasomal degradation of BET proteins, ARV-825 disrupts key oncogenic pathways, such as MYC and NF-κB signaling, leading to growth arrest and apoptosis in cancer cells." (PMID 39204415, 2024). "On the one hand, PVT1 and MYC locate at chromosome 8q24, which leads to co-amplification of them in various types of cancer." (PMID 39376555, 2024). "Previous research has shown that MYC regulates glutamine metabolism in various types of cancers, and drugs targeting these metabolic alterations have shown clinical potential." (PMID 39337668, 2024). "We then used a pan-serine/threonine phosphorylation antibody to assess the phosphorylation level of c-MYC in various cancer cells." (PMID 38622518, 2024). "More importantly, we identify several MYC-SL genes in the RNA transport pathway, apart from XPO1, which are yet to be targeted and can serve as rational, and specific targets against MYC-driven cancers." (PMID 38302473, 2024). "STK16 inhibition, either genetically or pharmacologically, effectively curtails cancer growth and c-MYC expression in vivo." (PMID 38622518, 2024). "In MYC-driven cancer cells, including G3-MB cells, ribosomal genes typically demonstrated higher expression levels than other genes." (PMID 39574899, 2024). "ZDHHC20 inhibits the chaperone-mediated autophagic degradation of YTHDF3 through S-palmitoylation of Cys474, which can result in abnormal accumulation of the oncogenic product MYC and thereby promote the malignant phenotypes of cancer cells." (PMID 38821916, 2024). "We additionally examined the association between the aggregated expression of MCR genes and MYC expression within the same cancer cells." (PMID 38877600, 2024). "SLC1A5 promotes the transport of glutamine leucine and Trp in cancer cells and controlled by mTORC1 and MYC signalling pathway." (PMID 39648156, 2024). "While c-MYC is required for active proliferation of both normal and cancer cells, p21 is a potent cell cycle inhibitor." (PMID 39550391, 2024). "High MYC expression in cancer cells also upregulates the transcriptional activator MondoA, thereby promoting lipid biosynthesis." (PMID 38721006, 2024). "Human cancers overexpress c-MYC in 70% of cases, due to alterations in signal transduction pathways, such as STAT3 pathway, or due to genomic aberrations, such as amplifications and translocations." (PMID 39769907, 2024). "M4N is a dual inhibitor of SP1 and HIF1A but only occasionally works as a MYC inhibitor for certain cancer cells specifically." (PMID 39590335, 2024). "Sulfopin-dependent inhibition of PIN1 was shown to downregulate the expression of MYC target genes in several cancer cell lines." (PMID 39093942, 2024). "There are a huge number of reviews describing the search for MYC inhibitors and their application to cancer treatment." (PMID 38510176, 2024). "MYC is a proto-oncogene that is constitutively and aberrantly expressed in over 70% of human cancers." (PMID 38662248, 2024). "MYC is one of the most common oncogenes in human cancers, exerting its growth-promoting effects primarily by enhancing ribosome biogenesis and mRNA translation." (PMID 39085650, 2024). "In EBV-positive HIV-associated DLBCL, mutations in JAK/STAT pathway also leads to abnormal activation and elevated expression of downstream oncogenes, such as c-MYC, thereby resulting in the progression of malignant tumors." (PMID 38284893, 2024). "The MYC, KIT and KRAS genes, all of which are implicated in various cancers, comprise G4-forming sequences within their promoters." (PMID 38407356, 2024).
cancer (continued). "Overexpressed MYC, observed in several types of cancer, activates target genes of glycolysis, mitochondrial biogenesis/oxidative phosphorylation (OXPHOS), glutamine metabolism, de novo nucleotide synthesis, and many other metabolic pathways." (PMID 39872506, 2024). "Certain lncRNAs have been shown to regulate MYC translation in cancer types other than CRC, although similar phenotypes suggest these mechanisms also operate in CRC cells." (PMID 39075086, 2024). "By extension to pNET cells, we found that MUC1-C also regulates E2F and MYC signaling pathways, which contribute to uncontrolled proliferation in cancer cells." (PMID 39062082, 2024). "In such co-treatments, MYC-driven cells can undergo apoptosis, autophagy, pyroptosis, or ferroptosis, ensuring cancer cell elimination, even if they escape one of the targeted pathways." (PMID 37450923, 2024). "Public CRISPR dependency data (depmap.org) identifies IKZF3 and MYC as dependencies in MM cell lines (n = 18), compared to cell lines derived from various other cancers." (PMID 38610997, 2024). "Overall, a range of studies highlights the direct role of MYC in regulating multiple cell- autonomous tumorigenic mechanisms in KRAS-driven cancers, indicating potential vulnerabilities under its cooperation." (PMID 39164274, 2024). "USP28 acts as an oncoprotein by stabilizing crucial oncoproteins in cancers, such as the transcription factor c-MYC." (PMID 38711144, 2024). "We identify a compound that degrades MYC, A80.2HCl, which induces MYC degradation at nanomolar concentrations, restores pRB1 protein levels and re-establish sensitivity of MYC high-expressing cancer cells to CDK4/6i." (PMID 38424044, 2024). "Dysregulation of MYC implicates a wide array of diseases including neurodegenerative diseases, immune disorders, and cancers." (PMID 38390324, 2024). "MYC and WNT7B are implicated in the signaling related to the self-renewal and differentiation of cancer stem cells." (PMID 38670944, 2024). "There is huge potential, therefore, for using MYC inhibitors that are currently being developed in the cancer field." (PMID 38510176, 2024). "Lactate can be transported away from cancer cells through MYC-activated MCT1 (SLC16A1 solute carrier family 16 member 1 aliase) and MCT2 (SLC16A7 solute carrier family 16 member 7 aliase) channels." (PMID 37450923, 2024). "Due to its undeniable role in driving and perpetuating tumorigenesis, MYC has been marked as a “most-wanted” target in cancer therapy." (PMID 39164274, 2024). "In summary, as observed in cancer but not limited to it, MYC’s role in promoting multiple physiological processes means that its overexpression, deregulation, or insufficiency can lead to an array of human diseases and disorders." (PMID 38510176, 2024). "To discover potential relationships, we calculated the correlation between MYC dependency and all other genes on a pan-cancer level." (PMID 38326887, 2024). "Although our findings cannot be directly compared to prior work in MYC-driven cancers, our studies clearly show that perturbing TADA2B impairs SAGA complex KAT activity regardless of which KAT is associated." (PMID 38820154, 2024). "WNT signalling was previously shown to induce enhancer-promoter looping at the MYC gene in cancer cells." (PMID 38607047, 2024). "Herein, we summarize and discuss the capacities of MYC in various cancer processes, including immune responses, metabolism, the cell cycle, apoptosis, autophagy, pyroptosis, metastasis, angiogenesis, multidrug resistance (MDR), and intestinal flora." (PMID 37450923, 2024). "The results indicated that the gain of STK16 enhanced the proliferation ability of cancer cells, while c-MYC silencing counteracted this effect." (PMID 38622518, 2024).
cancer (continued). "The SEC is not only required for rapid induction of cellular transcription, for example, in response to stress and for transcription in cancer driven by the protooncogene MYC, but also for secretory‐specific immunoglobulin heavy chain production." (PMID 39582094, 2024). "Given the importance of the MYC-HIF interplay in cancer cells, it would be critical to further understand how these proteins precisely interact with each other to jointly regulate the expression of metabolic genes." (PMID 38904014, 2024). "On the other hand and in contrast with the results above, transgenic mice engineered with near-complete elimination of MYC at weaning, named MycKO mice, aged prematurely yet lived longer with decreased cancer incidence." (PMID 38510176, 2024). "MYC is reportedly a grand orchestrator of cancer growth and immune evasion, as it regulates most of these traits by modulating its gene targets." (PMID 38390324, 2024). "Pioneering work by the Hurley group demonstrated that small molecules stabilizing G4 structures can inhibit c-MYC transcription, highlighting G4s as a promising anti-cancer target." (PMID 39027314, 2024). "Its elevated or deregulated expression has been associated with a wide range of aggressive human cancers including breast carcinoma, lung carcinoma, and neuroblastoma; additionally, MYC expression is known to influence many of the hallmarks of cancer." (PMID 38236931, 2024). "The activated mTOR also enhances MYC translation and function in transcribing genes favoring cancer progression." (PMID 38390324, 2024). "The growing body of evidence of the vastness of the “onco-MYC network” and its grave implications on cancer progression point to MYC being an ideal therapeutic target." (PMID 38390324, 2024). "Intriguingly, a reciprocal enhancement exists where MYC upregulates SIRT2 in cancer cells, establishing a feedback loop that fosters MYC‐centric transcription and oncogenic activity." (PMID 38374872, 2024). "Our previous works validated the efficacy of KRAS- and MYC-targeting PPRHs, which provoked gene silencing and resulted in the death of cancer cells with deregulated KRAS and/or MYC." (PMID 39457457, 2024). "MYC overexpression in cancer is attributable to the fact that glutamine is necessary for cell growth and genetic events." (PMID 37450923, 2024). "The MYC oncogene (also known as c-Myc) is part of a superfamily of genes whose products are among the most commonly activated in human cancers." (PMID 38416262, 2024). "Of interest, MYC governs oncometabolism through the interactions with its partners and cofactors, as well as cancer immunity via its gene targets." (PMID 38390324, 2024). "Beyond our identified interchromosomal insertion of the MYC locus, the intricate aneuploidy patterns commonly observed in cancer pose a challenge that existing standard software and pipelines struggle to effectively address." (PMID 38076897, 2024). "CBLL1 silencing was confirmed at the mRNA level, and mRNA downregulation of other known stem cell markers including LGR5, NANOG and c-MYC was also detected in sh-CBLL1 HT29 cancer stem cell tumourspheres compared to sh-control tumourspheres." (PMID 38339195, 2024). "One of the most common changes occurring in CRC and over 70% of other cancers involves the abnormal expression and/or activity of MYC, attracting a great deal of research attention." (PMID 39075086, 2024). "MYC expression is elevated in as many as seventy percent of cancers, and it is one of the most commonly studied targets for cancer therapy." (PMID 39687864, 2024). "In turn, this emphasizes the importance of dissecting the “life cycle” of MYC in cancer, understanding its key downstream targets, and how MYC itself is dysregulated." (PMID 39075086, 2024). "These marker genes play diverse roles in cancer, such as promoting growth and proliferation (MYC, HIF1A, ATM), inhibiting apoptosis (MCL1, BIRC3, BCL2) and facilitating invasion (CXCR4, CD55)." (PMID 38982317, 2024).